5_8S_rRNA (5.8S ribosomal RNA )
Synonyms: RNA5-8SP; LOC110467523
Gene: Ribosomal RNA gene on chromosome 20 (30,484,925 to 30,485,076, reverse strand). Ensembl gene ENSG00000275877.
Gene Ontology:
Molecular function: structural constituent of ribosome
Cellular component: ribosome
Homologues: Orthologues: chimpanzee 5_8S_rRNA (94% identical), zebrafish 5_8S_rRNA (88% identical), zebrafish si:dkeyp-3b12.15 (88% identical), rat 5_8S_rRNA (87% identical), zebrafish 5_8S_rRNA (87% identical), rat 5_8S_rRNA (86% identical), rat 5_8S_rRNA (85% identical), rat 5_8S_rRNA (84% identical), rat 5_8S_rRNA (83% identical), rat 5_8S_rRNA (82% identical), mouse Gm54867 (81% identical), rat 5_8S_rRNA (81% identical), and 1 more. Paralogues in human: 5_8S_rRNA (94% identical), 5_8S_rRNA (93% identical), 5_8S_rRNA (91% identical), RNA5-8SN1 (91% identical), RNA5-8SN2 (91% identical), RNA5-8SN3 (91% identical), RNA5-8SN4 (91% identical), RNA5-8SN5 (91% identical), 5_8S_rRNA (88% identical), 5_8S_rRNA (85% identical).